EGFR (epidermal growth factor receptor)
Diseases named in the same sentence as EGFR in open-access papers (continued):
Sharing a sentence is not in itself a finding about the gene and the disease.
oral cancer (continued). "EGF was previously found to strongly stimulate migration in several oral cancer cells, including E10, and transactivation of EGFR has been found to be part of the mechanism of mitogenic effects of GPCRs in several cancer cells." (PMID 24928086, 2014). "In a third oral carcinoma cell line, D2, LPA caused rapid EGFR transactivation, like in E10 cells, but D2 cells have a very high migratory activity in the absence of any stimulation, and LPA is rather slightly inhibitory." (PMID 24928086, 2014). "Cetuximab is the only approved targeted therapy available for oral cancer, which targets epidermal growth factor receptor (EGFR) involved in cell growth." (PMID 25029526, 2014). "Dysregulated epidermal growth factor receptor (EGFR)-phosphoinositide-3-kinase (PI3K)-AKT signaling is considered pivotal for oral cancer, and the pathway is a potential candidate for therapeutic targeting." (PMID 23806066, 2013). "In search of a possible mechanism by which decorin is aberrantly localized in the nucleus, we sought out to determine if nuclear decorin interacts with nuclear EGFR in our oral cancer model." (PMID 21958730, 2011). "Aberrant expression and nuclear localization of EGFR has been demonstrated by many different groups in a variety of human cancers including oral cancer." (PMID 21958730, 2011). "Taken together, EGFR activation is an alternative mechanism that induces β-catenin translocation to the nucleus of certain oral cancer cells." (PMID 20302655, 2010). "EGFR signaling regulates β-catenin localization and stability, target gene expression, and tumor progression in oral cancer." (PMID 20302655, 2010). "This implicates the EGFR signal in mediating entry of β-catenin into the nucleus and progression of oral cancer." (PMID 20302655, 2010). "The present study demonstrated that the EGFR signal participates in the dysregulation of β-catenin in oral cancer." (PMID 20302655, 2010). "We examined the role of epidermal growth factor receptor (EGFR) signaling in the accumulation of β-catenin in the nuclei of oral cancer cells." (PMID 20302655, 2010). "In theory this should be achieved in oral cancer patients by the use of EGFR antibody since this antibody should target the differentiated oral tumors whereas stem cells should be eliminated by the activated NK cells." (PMID 20661281, 2010). "To investigate the effect of the EGFR signal on β-catenin redistribution, we used two lines of oral cancer cells, SAS and OECM1." (PMID 20302655, 2010). "We also studied the expression of EGFR, β-catenin, and cyclin D1 in 112 samples of oral cancer by immunostaining." (PMID 20302655, 2010). "Since most oral cancers are epithelial in origin, it is reasonable that they should have a high probability of expressing EGFR." (PMID 20579333, 2010). "In the present paper, we describe the effect of EGFR signaling on the nuclear accumulation of β-catenin in oral cancer." (PMID 20302655, 2010). "Consistent with other reports, we found that both EGFR and Her-2 were overexpressed in a subset of oral cancer patients (58 and 41%, respectively)." (PMID 12915878, 2003). "There was a strong correlation between EGFR and Mcl-1 expressions in oral cancer patients." (PMID 38888847, 2025). "Afatinib treatment induced apoptosis and suppressed Mcl-1 in oral cancer cell lines without the EGFR T790M mutation." (PMID 38888847, 2025). "For example, oral cancer cells often have specific molecular markers, such as EGFR (Epidermal Growth Factor Receptor) or human papillomavirus-associated markers, and targeted therapies can selectively target these markers to inhibit cancer cell growth while protecting normal cells." (PMID 40284275, 2025).
oral cancer (continued). "Taken together, these results indicate that EGFR and Mcl-1 are correlated and coexpressed in oral cancer, suggesting that both factors may contribute to poor prognosis among oral cancer patients." (PMID 38888847, 2025). "The present study investigates the efficacy of FMD combined with EGFR-TKI therapy in oral cancer." (PMID 40808689, 2025). "We investigated whether FMD medium enhances the effects of the EGFR inhibitor gefitinib on oral cancer in both 2D and 3D cell spheroid models." (PMID 40808689, 2025). "Our findings suggest that targeting the EGFR/mTOR/Mcl-1 axis with afatinib could be a promising therapeutic strategy for oral cancer treatment, particularly in patients with high EGFR and Mcl-1 co-expression." (PMID 38888847, 2025). "Oral cancer cell lines exhibit different EGFR phosphorylation responses to hypoxia." (PMID 40940319, 2025). "By targeting both EGFR-mediated survival pathways and the mitotic checkpoint, this combination therapy aims to enhance the overall anti-cancer effect, leading to increased cancer cell death and improved treatment outcomes in oral cancer." (PMID 39594688, 2024). "Interestingly, our research group has previously recognized these compounds as potential EGFR-TK inhibitor candidates for the treatment of oral cancer." (PMID 38529190, 2024). "Recently, a strategy targeting the epidermal growth factor receptor (EGFR), which is overexpressed and contributes to the aggressive behavior of oral cancer, has shown beneficial results, particularly in advanced or recurrent cases where other therapies are no longer effective." (PMID 38791040, 2024). "Similarly, epidermal growth factor receptor (EGFR)-targeted ZnO nanoparticles have been explored for the precise targeting of EGFR-overexpressing oral cancer cells." (PMID 38893579, 2024). "Furthermore, inhibiting FBLIM1 was revealed to hinder oral cancer cell proliferative, migratory, and invasive properties via modulating the pathway that is controlled by EGFR." (PMID 38152333, 2023). "Recent studies have also demonstrated the noticeable overexpression of EGFR in oral cancer cells." (PMID 39144672, 2023). "Several studies have investigated the role of EGFR in the pathogenesis of oral carcinoma." (PMID 37370896, 2023). "We presented preclinical and clinical data to demonstrate how repurposing EGFR inhibitors typically used for cancer treatment could be an effective pharmacological strategy to treat oral cancer pain and to prevent or delay the development of opioid tolerance." (PMID 38004424, 2023). "Likewise, a cell culture study revealed that the NFAT5 transcription factor is able to promote oral cancer cell proliferation via changes in the subcellular localization of the epidermal growth factor receptor." (PMID 35955417, 2022). "The main molecular target drugs available for oral cancer in Japan are cetuximab, a mouse monoclonal antibody targeting epidermal growth factor receptor (EGFR), and nivolumab, an immune checkpoint inhibitor that blocks the programmed death-1 (PD-1) and PD-ligand 1 (PD-L1) pathways." (PMID 35330413, 2022). "mRNA levels of TGFα and EGFR also increased in the normal mucosa of oral cancer patients, suggesting that TGFα/EGFR gene transcription is an early event of carcinogenesis or could be a foundation to a tumour." (PMID 35681586, 2022). "Research provided evidence that mRNA and protein levels of TGFα and EGFR increased in oral cancer patients in comparison to disease-free controls and poor prognosis might be related to this elevation level of TGFα and EGFR." (PMID 35681586, 2022). "Thus, there is a tremendous need for a highly effective and well-tolerated chemopreventive agent against oral cancer which can modulate the EGFR pathway." (PMID 36008552, 2022). "Moreover, another cohort from the TCGA database found that oral cancer patients with high co-expression of EGFR and SQSTM1 had poor DSS (AHR = 2.53, 95% CI = 1.46–4.39, p = 0.001) but not DFS." (PMID 34830108, 2021).
oral cancer (continued). "The resistance of oral cancers to anti-EGFR therapies could therefore be related to the overexpression of ITK, as indicated in the previous study of NSCLC." (PMID 34283052, 2021). "EGFR expression was the highest in cancers of the oral cavity and the lowest in glottis cancers." (PMID 35002542, 2021). "Scheff and colleagues demonstrated that the supernatant of some oral cancer cell lines is sufficient to induce nociceptive behavior in mice, which was attenuated by EGFR inhibition, and that this supernatant contained higher levels of ADAM17 than non-nociceptive cell lines." (PMID 34054523, 2021). "Therefore, it is difficult to consider that antitumor effects would be obtained by blocking EGFR signaling alone in patients with oral cancer." (PMID 32878053, 2020). "However, as observed in the EGFR expression in the A431 cells, it was confirmed that the oral cancer cells express not only full-length EGFR but also EGFR lacking the intracellular domain." (PMID 32878053, 2020). "However, we provide the first evidence of epigenetic impact on overexpression of EGFR in oral cancer." (PMID 33317464, 2020). "In the previous research of this study, mice were immunized with purified recombinant EGFR to produce an EMab-134 monoclonal antibody (mAb; IgG1, kappa), which reacted with the endogenous EGFR of oral cancers in flow cytometry, Western blotting, and immunohistochemistry." (PMID 32218834, 2020). "However, cetuximab was ejected by oral cancer cells in EVs that contained EGFR in response to therapy." (PMID 32150875, 2020). "Additionally, AurkA/AurkB and EGFR have the same downstream signaling pathways, rendering them both as a potential therapeutic target in oral cancer." (PMID 35047986, 2020). "However, we recently showed that anti-EGFR therapeutic antibody cetuximab is secreted with EVs by oral cancer cells, suggesting that cancer cells can secrete toxic and redundant substances within EVs as a novel mechanism underlying drug resistance." (PMID 30364132, 2018). "Likewise, the up-regulation of mir-31 in oral cancer is probably a result of epidermal growth factor receptor (EGFR) activation." (PMID 29482431, 2018). "Hence, this study directly links the smoking-induced miRNAs regulating the expression of HuR as well as EGFR that is considered as one of the prime targets for oral cancer therapy." (PMID 30289952, 2018). "Finally, immunohistochemical analyses with EMab-51 showed sensitive and specific reactions against oral cancer cells, warranting the use of EMab-51 to detect EGFR in pathological analyses of EGFR-expressing cancers." (PMID 28891752, 2017). "Furthermore, both FOXO1 and HBP1 mRNA levels were significantly lower in three EGFR over-expressing oral cancer cells tested than the normal human oral keratinocyte (HOK)." (PMID 28099936, 2017). "The EGFR/PI3K/Akt signaling is often up-regulated in malignant oral cancer." (PMID 28099936, 2017). "Consequently, inhibition of EGFR expression and its signaling are a promising therapeutic strategy for oral cancer patients." (PMID 29212184, 2017). "In addition, the FOXO1-HBP1 axis is a crucial downstream effector of the EGFR/PI3K/Akt signaling pathway in oral cancer." (PMID 28099936, 2017). "Anti-EGFR monoclonal antibody, cetuximab has been approved for treatment of oral cancer." (PMID 29212184, 2017). "However, in oral cancers, Ley has also been suggested to promote cell migration via stabilization of EGFR and downstream signaling." (PMID 26908442, 2016). "Recently, the elevated expression of EGFR and MAPKs is crucial in the pathogenesis of oral cancer." (PMID 26919242, 2016). "In a previous study, we demonstrated that quercetinappears to be a potent anti-tumorigenic agent through its inhibition of the EGFR/Aktpathway in oral cancer, but its anti-metastatic potential in HNSCC remains unclear." (PMID 27510965, 2016). "This indicates the upregulation of EGFR in the pathogenesis of oral carcinomas." (PMID 26697149, 2015).
oral cancer (continued). "Accordingly, EGFR is a promising target for treating oral cancer." (PMID 26462152, 2015). "In addition to overexpression of the ras oncogene family, which is linked to malignant transformation, EGFR, the receptor of EGF and TGF-α, is also commonly overexpressed in oral cancers." (PMID 24995269, 2014). "Furthermore, we show here that nuclear localized decorin interacts with nuclear EGFR in this oral cancer cell line model." (PMID 21958730, 2011). "Moreover, our data suggest that aberrant accumulation of β-catenin under EGFR activation is a malignancy marker of oral cancer." (PMID 20302655, 2010). "Epidermal growth factor receptor (EGFR) is a member of the receptor tyrosine kinase family, and overexpression of EGFR is associated with poor prognosis and progression of many human cancers, including oral cancer." (PMID 20302655, 2010). "EGFR is the most commonly overexpressed receptor tyrosine kinase in oral cancer." (PMID 20302655, 2010). "We used two strains of cultured oral cancer cells, one with reduced EGFR expression (OECM1 cells) and one with elevated EGFR expression (SAS cells), and measured downstream effects, such as phosphorylation of β-catenin and GSK-3β, association of β-catenin with E-cadherin, and target gene regulation." (PMID 20302655, 2010). "Our results indicate that 15d-PGJ2 targets JAK signalling independent of EGFR signalling and suggest that inhibition of IL-6-mediated JAK signalling and suppression of EGFR-independent Stat3 activation may represent a novel therapeutic approach in oral cancer." (PMID 15316561, 2004). "Similarly, CEACAM6 interacts with EGFR to modulate signaling in oral cancer upon ligand activation." (PMID 40856433, 2025). "We first examined whether hypoxia alone can induce EGFR phosphorylation in oral cancer cells." (PMID 40940319, 2025). "Consequently, combination therapy using SAMA and NK-1R antagonists, cisplatin, EGFR inhibitors, and radiation may synergistically improve oral cancer treatment with low side effects towards normal cells." (PMID 38399445, 2024). "Thus, EGFR tyrosine kinase inhibitors, such as Erlotinib 49, and EGFR monoclonal antibodies, such as cetuximab 50, have investigated the antitumor activity against human oral cancer." (PMID 37497406, 2023). "Despite routine therapies for oral cancers involving multi-disciplinary approaches including surgical resection combined with chemotherapy, radiotherapy or targeted therapy such as cetuximab that targets epidermal growth factor receptor (EGFR), clinical prognostic outcome is far from satisfactory." (PMID 35706019, 2022). "In addition to a combination of surgery, radiotherapy or chemotherapy as the standard therapy of choice for this disease, a monoclonal antibody that is intended to target the epidermal growth factor receptor (EGFR) has been shown to elevate the efficacy of radiotherapy in oral cancer treatment." (PMID 35806120, 2022). "A previous study showed that IL‐1β could activate EGFR via the CXCL1‐CXCR2 axis in oral cancers." (PMID 33955688, 2021). "Most of the mutations in EGFR are not functionally validated in oral cancers, and the well-known mutations associated with tyrosine kinase inhibitor (TKI) sensitivity/resistance, such as G719X, T790M, exon 19 deletion/insertion, exon 20 insertions, L858R and L861Q, have not been found in OSCC34,41." (PMID 30914776, 2019). "Hence, we studied whether FOXO1 activation of the HBP1 promoter is also under the control of the upstream regulator Akt in the HSC-3 oral cancer cell line with an aberrant activation of the EGFR/PI3K pathway." (PMID 28099936, 2017). "Targeting Ley on EGFR could have a potential therapeutic effect on oral cancer." (PMID 25799278, 2015).
oral cancer (continued). "Therefore, EGFR is proposed to be a target for anticancer therapy in oral cancer." (PMID 25799278, 2015). "Whether EGFR, Src and Ras are important in this event awaits further investigation, because the mutation and elevated expression of CYP, COX2, EGFR, Src and Ras in oral cancer and precancer are reported." (PMID 25051199, 2014). "Therefore, our results suggest that the EGFR signal enhances accumulation of β-catenin in the nuclei of oral cancer cells directly, by phosphorylation of β-catenin, and indirectly, by stabilization of β-catenin through phorsphorylation and inhibition of GSK-3β." (PMID 20302655, 2010). "EGFR signaling, a key mediator of the PI3K/AKT and MAPK/ERK pathways, is known to contribute to cisplatin resistance and progression in oral cancer." (PMID 41044643, 2025). "Combining Cetuximab with BAY1217389 enhances mitotic cell death, indicating that inhibiting EGFR and MPS-1 disrupts critical signaling required for cell division and survival in oral cancer cells." (PMID 39594688, 2024). "EGFR, MPS-1, Aurora-B, and KSP are highly expressed in oral cancer cells and tissues from OSCC patients, which is in accordance with the data available in bioinformatic databases, such as UALCAN." (PMID 39594688, 2024). "EGFR-targeting erlotinib in combination with VEGF inhibitors also showed promising results in phase I and II trials in metastatic and recurrent oral cancers." (PMID 38414024, 2024). "Globally, the overexpression of EGFR, MPS-1, Aurora-B, and KSP in oral cancer cell lines highlights the relevance of their targeting to potentiate current oral cancer treatments." (PMID 39594688, 2024). "In our study, we observed that intervention with solanine affected the EGFR-mediated PI3K/Akt/NF-κB signaling pathway, effectively reducing inflammation, cell proliferation, and angiogenesis in aggressive drug-resistant oral carcinoma cells." (PMID 39124760, 2024). "For instance, cetuximab, a monoclonal antibody targeting epidermal growth factor receptor (EGFR), was approved as a targeted drug for unresectable or chemoresistant oral cancers." (PMID 37686580, 2023). "The data summarized here were retrieved from PubMed with keywords search for EGFR + pain, EGFR + morphine tolerance, EGFR + oral cancer, MOR+ morphine tolerance, NMDAR + pain, NMDAR + MOR, and NMDAR + EGFR." (PMID 38004424, 2023). "Among these, HIF1α, CDH1, CD44, EGFR, and CCND1 were identified as the top hub genes that have also been reported as driver candidates responsible for oral cancer initiation and progression." (PMID 37316916, 2023). "Oral cancer cells were much less able to proliferate, migrate, and invade when FBLIM1 was knocked down, and this suppression was achieved by modification of the EGFR pathway." (PMID 38152333, 2023). "Knockout of HSD11B2 promoted tumor angiogenesis (expression of EGFR and VEGFA), cell proliferation, and invasion in oral cancer cells." (PMID 36631756, 2023). "Although EGFR is expressed in the normal oral epithelium as well as in the majority of OSCC cells, it is also a therapeutic target for the treatment of oral cancer." (PMID 35681586, 2022). "EMT process can significantly contribute to chemoresistance such as cisplatin, doxorubicin, and EGFR-TKI treatment in many cancer types, including lung, breast hepatocellular carcinoma, ovarian, and oral cancers." (PMID 35457185, 2022). "It is worth specifically examining the biomarker role of CXCL10/STAT2 in responses to anti-EGFR and ICB-based therapies in oral cancer patients." (PMID 35207629, 2022). "Another study reported the inhibition of cell proliferation and migration in oral cancer cells (H400 and H357) by EGCG treatment through reduced expression of phosphorylated epidermal growth factor receptor (EGFR)." (PMID 35883653, 2022).